KRAS (KRas proto-oncogene, GTPase)
Diseases named in the same sentence as KRAS in open-access papers (continued):
Sharing a sentence is not in itself a finding about the gene and the disease.
tumor (continued). "Wild type COLM-5 cells and KRAS codon 12 mutated Capan-1 cells (each 500 cells) were spiked into normal healthy blood (2 ml) and resultant isolated spiked tumor cells by 3D filter device were successfully analyzed for KRAS mutation." (PMID 24523941, 2014). "This interaction of KRAS mutation and primary tumor location was found to be significant for both OS and PFS." (PMID 24816724, 2014). "In that patient, tissue was available (both pre- and post-treatment tumors) and only the post-treatment tumor showed a KRAS mutation." (PMID 25119929, 2014). "We sought to investigate the methylation profile associated with KRAS mutant tumors and its association with tumor multiplicity." (PMID 24643221, 2014). "We assessed the clinical factors, including type of KRAS mutation and treatment, of patients with advanced cancer and tumor KRAS mutations and their association with treatment outcomes." (PMID 25313136, 2014). "Of interest, most NRAS (5 of 6) and all BRAF (3 of 3) mutations clustered in ICC tumour subtype and were mutually exclusive with KRAS (15.7%)." (PMID 24867389, 2014). "A tumor of pure lepidic component is now considered adenocarcinoma-in-situ, so the fact that KRAS mutations were identified only in the minority invasive acinar component and not in the lepidic component suggests an evolutionary event in this patient." (PMID 24742923, 2014). "Cox regression models with hazard ratios for primary tumor location, KRAS mutation and interaction respectively as explanatory variables were analyzed." (PMID 24816724, 2014). "Interaction analysis revealed a significant difference between sexes for BMI and risk of KRAS-mutated tumours (pinteraction = 0.044)." (PMID 24918610, 2014). "A significant interaction was found between sex and BMI with respect to risk of KRAS-mutated tumours." (PMID 24918610, 2014). "Here, we use mRNA encoding human tumor inducers (Gli1, XRel3, KRAS) in Xenopus laevis embryos to initiate growth of tumor like structures (ITLS) that highly resemble classic tumors." (PMID 24830454, 2014). "This suggests that KRAS mutations confer only part of the advantage needed for tumor cell survival with additional survival signals presumably deriving from multiple signaling pathways." (PMID 25090459, 2014). "We found that there was a trend to improved survival in patients with KRAS wild-type tumours versus those with KRAS mutated tumours in the XELOX/bevacizumab subgroup but in the FOLFOX/bevacizumab subgroup." (PMID 24884897, 2014). "Our objectives were to assess the clinical factors, including type of KRAS mutation and treatment, of patients with tumor KRAS mutations and their association with treatment outcomes." (PMID 25313136, 2014). "A Cox regression model was used to evaluate interaction between primary tumor location and KRAS mutation." (PMID 24816724, 2014). "In men, several anthropometric measures were associated with both KRAS-mutated and KRAS wild type tumours." (PMID 24918610, 2014). "Poor prognosis and significant association with Dukes' stage D suggest that tumours with KRAS and PIK3CA mutations are more likely to develop into liver metastasis." (PMID 25361007, 2014). "Clinical studies should explore the clinical significance of additional alterations in patients with tumor KRAS mutations." (PMID 25313136, 2014). "Among the AGC patients whose tumor tissue contained gene mutations, multiple mutations of KRAS codon 13, PIK3CA codon 545 and NRAS codon 12 were detected in only one case." (PMID 24774510, 2014). "Consistent detection of KRAS mutations was achieved in samples containing at least 10 tumor cells/7.5 ml of blood." (PMID 25137394, 2014). "KRAS mutations were more frequent in tumor tissue than in plasma (sequencing, 38% vs. 17%, p < 0.001; PNA-PCR, 47% vs. 31%, p < 0.001)." (PMID 25491325, 2014).
tumor (continued). "MEK is known to be a downstream effector of KRAS signalling and has been implicated in cell proliferation and tumour growth." (PMID 24956168, 2014). "In vitro and in vivo assays have established that miR-96 decreases cancer cell invasion and migration and slows tumor growth in a manner associated with KRAS gene downregulation." (PMID 24678958, 2014). "While all anthropometric measures except height were associated with an increased risk of KRAS-mutated tumours, only BMI was associated with an increased risk of KRAS wild type tumours overall." (PMID 24918610, 2014). "Routine assessment of KRAS mutational status is generally performed in tumor samples and used to personalize treatment in patients with mCRC." (PMID 25491325, 2014). "The dependence of CB42 on mutated KRAS was illustrated by the observed potent and significant tumor growth inhibition when treated with a MEK inhibitor, PD0325901, which has been shown to strongly inhibit KRAS driven cancers." (PMID 25162504, 2014). "This case indicates that this specific double mutation of BRAF V600E and KRAS G12A results in a poor clinical course, potentially through the acceleration of tumor progression." (PMID 25013473, 2014). "In nude and SCID mice with advanced human KRAS-mutated A549 metastatic lung cancer, pre-nebulization with AvidinOX enables biotinylated Cetuximab to control tumor growth at a dose lower than 1/25,000 the intravenous effective dose." (PMID 25238453, 2014). "In three cases, the KRAS mutation differed between the primary tumor and the metastases; one of these patients had a Gly13Asp KRAS mutation, whereas the liver metastasis had a Gly12Ser mutation." (PMID 24668895, 2014). "In general, the mutual exclusivity of mutations of NRAS and KRAS in varied tumor types suggests that they provide similar or identical oncogenic signals." (PMID 25361007, 2014). "PNA-PCR was able to detect KRAS mutations in an additional 39 tumor and 35 plasma samples where direct sequencing failed." (PMID 25491325, 2014). "In the absence of ZNF304, these tumor suppressor genes remained switched on in cancer cells with the KRAS mutation, so the growth of the tumor was slowed down." (PMID 24623306, 2014). "We show that Sox9 is overexpressed within the lung ADC subgroup that harbors KRAS mutations, and confirm that Sox9 is overexpressed within the more malignant portions of tumor from the LSL-K-rasG12D lung ADC mouse model." (PMID 25004243, 2014). "In PDAC, mutation-driven KRAS over-activation is a very early alteration present in almost all tumours." (PMID 24393789, 2014). "It has been suggested that the resistance mutations in KRAS and other genes were highly likely to be present in a clonal subpopulation within the tumours prior to the initiation of panitumumab therapy." (PMID 25361007, 2014). "Among the remaining 708 unpaired patients, one case (0.1%) only presented coexistence of two KRAS mutations (G12D and Q61L) in the same tumor tissue." (PMID 25202344, 2014). "Apparently, the real mechanism by which different KRAS mutations affect tumor biology and lead to different outcomes needs to be further elucidated." (PMID 25367198, 2014). "KRAS mutations were detected in 72 tumours (31.9%), mostly in exon 2, in codon 12 in 45 cases (20.0%) and in codon 13 in 16 cases (7.0%), while BRAF V600E mutations were found in 6 cases (2.6%)." (PMID 23374602, 2013). "The beneficial prognostic impact of KRAS mutation was ony evident in tumours of low-intermediate differentiation grade (p = 0.023), and in a less advanced clinical stage (p = 0.014)." (PMID 23800114, 2013). "Constitutively active KRAS mutations have been found to be involved in various processes of cancer development, and render tumor cells resistant to EGFR-targeted therapies." (PMID 23355875, 2013).
tumor (continued). "In the TITAN study, there was some evidence for a higher risk of death in KRAS mutant tumor patients treated with erlotinib compared to chemotherapy but there was no elevated risk of tumor progression." (PMID 23922984, 2013). "Tumor samples were screened for KRAS codon 12, 13 and BRAF V600E mutations by SNaPshot and/or direct sequencing." (PMID 23497191, 2013). "The KRAS mutation status and the clinical and pathological tumor features were assessed in a total of 65 patients." (PMID 29147353, 2013). "A single KRAS or EGFR mutation analysis was performed in the tumor samples of 18 and 5 patients, respectively." (PMID 23922984, 2013). "KRAS mutations seem to occur early in the development of low-grade tumours, since they can be found in benign and borderline areas within the same neoplasm." (PMID 23800114, 2013). "A small number of available experimental data demonstrate that tumor clones carrying KRAS codon 13 mutations are less aggressive than those carrying codon 12 mutations." (PMID 23437064, 2013). "Tumor characteristics, including KRAS mutation status as well as EGFR expression and phosphorylation levels, have been reported previously." (PMID 23935914, 2013). "Characteristics that predicted engraftment in NSCLC included squamous histology, poor differentiation, larger tumor size, and KRAS mutation." (PMID 23981300, 2013). "KRAS mutation analyses performed by direct sequencing revealed KRAS mutations in codon 12/13 in the tumor tissue of 8/24 patients (33%)." (PMID 24137455, 2013). "A comparison between the KRAS mutational status in CTCs and the corresponding tumor tissue was performed." (PMID 24179521, 2013). "The aim of the present study was to examine the occurrence, clinicopathological correlates and prognostic significance of KRAS mutation status in tumours from 154 incident EOC cases from two prospective, population-based cohorts." (PMID 23800114, 2013). "For example, loss of ATM results in a decreased expression of the tumor suppressive miRNAs, miR- 96, which is known to target KRAS, and the miR-29 family, which includes miR-29b-1, miR-29b-2, and miR-29c." (PMID 23741392, 2013). "Mutations in the KRAS gene are among of the most prevalent in human tumours and they are known to have pleiotropic effects on tumour biology." (PMID 23506169, 2013). "Clustering of the tumours (horizontal axis) showed them to be separated into two main groups, where the main discriminating molecular variable was KRAS mutation; all the mutants were present in the second cluster and none of the first cluster was mutant." (PMID 23165447, 2013). "Specifically, loss of Atg7 in KRas driven lung cancers caused accumulation of damaged mitochondria, defective fatty acid oxidation, and a growth arrest that retarded tumor growth." (PMID 24350057, 2013). "Binary logistic regression was performed to assess the likelihood of liver metastasis as a function of the primary tumor site (colon or rectum) and KRAS mutation status (mutated or wild-type)." (PMID 29147353, 2013). "Die Immunohistochemische Expression für MAPK war nicht empfindlich oder spezifisch genüg um den KRAS mutations Status des Tumor genau vorauszusagen." (PMID 23388101, 2013). "It is evident from recent clinical data from the phases II and III trials for panitumumab and cetuximab, where patients whose tumours harbour mutations in KRAS are less likely to respond to treatment." (PMID 23356214, 2013). "In contrast, one lung sample predominantly displayed mutant signals in the tumor regions, potentially reflecting KRAS homozygous mutation or loss-of-heterozygosity (LOH), while the few existing wild-type signals originated from the stroma." (PMID 24280411, 2013). "The borderline significant inverse association of KRAS mutation and high expression of Chek1 is well in line with the association of KRAS wild-type tumours being more genetically unstable." (PMID 23800114, 2013).
tumor (continued). "KRAS codon 12,13 and 61 mutations were analysed by pyrosequencing in tumours from 163 incident EOC cases in the Malmö Diet and Cancer Study and Malmö Preventive Project." (PMID 23800114, 2013). "Using HRM and TaqMan warrants high-quality and rapid-routine KRAS mutation detection in paraffin-embedded tumor specimens." (PMID 24133623, 2013). "A multivariate Cox regression model that included age, gender, TNM, tumor grade and tumor histology as co-variants confirmed KRAS mutational status as a potential independent prognostic marker with a hazard ratio (HR) of 1.87 (95%CI 0.99–3.51, P = 0.05)." (PMID 23565280, 2013). "The analysis of tumour samples for KRAS mutations is undertaken using samples of fresh-frozen or paraffin-embedded tumour material." (PMID 23356214, 2013). "Mutations in codon 12 of the KRAS gene were conserved from primary tumor (F0) through the F2 generation of all twenty tumorgraft models evaluated." (PMID 24194913, 2013). "The concordance between the KRAS mutation profile of the primary tumor and the profile of the corresponding metastases is high (90%), suggesting that these active somatic mutations are acquired early during carcinogenesis and before metastasis." (PMID 29147353, 2013). "DNA from corresponding FFPE tumor sections were thereafter tested for KRAS mutations by pyrosequencing, and the results were concordant with the in situ assay." (PMID 24280411, 2013). "Subtle changes in the molecular nature of KRAS oncogene activating mutations occurring in tumour cells have a major impact on the vascular strategy devised providing with new insights on the role of KRAS mutations on angiogenesis." (PMID 23506169, 2013). "The presence of KRAS mutations was associated with poor survival in tumor stage III (HR = 1.94, P = 0.03)." (PMID 23565280, 2013). "Kaplan-Meier analysis revealed a significantly improved OCSS for patients with KRAS-mutated compared to KRAS wild-type tumours (p = 0.015)." (PMID 23800114, 2013). "Based on these and other studies, the American Society of Clinical Oncology recommended that patients who are candidates for anti-EGFR therapy should have their tumour tested for KRAS mutation." (PMID 23356214, 2013). "KRAS mutation analysis in codons 12 and 13 was performed in the tumor tissue of 94/150 patients, and BRAF mutation analysis in codon 600 was performed in 83/150 cases." (PMID 23637996, 2013). "Within those models with EGFR and KRAS mutation, the anti-tumor efficacy of the EGFR tyrosine kinase inhibitor, gefitinib, was consistent with published preclinical data and clinical responses." (PMID 23842453, 2013). "Nevertheless, our observations indicate that CSMD1 nonsynonymous mutations provide tumor cells with a selective advantage, which operates independently of the advantage provided by KRAS mutations." (PMID 23505554, 2013). "Approximately 40% of mCRC patients are likely to have a KRAS mutation in their tumor, suggesting treatment should be tailored based on KRAS status." (PMID 24403261, 2013). "In line with previous findings, we found a strong association between KRAS mutations and more well-differentiated tumours." (PMID 23800114, 2013). "In pancreatic cancer, activated KRas is linked to reprograming of tumor metabolism both through increased glycolytic flux to lactate, hexosamine biosynthesis, and non-oxidative pentose phosphate pathway." (PMID 24350057, 2013). "Yet, other studies have suggested that there is significant heterogeneity in the expression of KRAS mutations within a tumour and also between primary tumour samples and lymph node metastases." (PMID 23356214, 2013). "Subsequently, whole genome sequence analysis on this patient’s tumour confirmed mutation in KRAS p.G12V." (PMID 24004612, 2013). "CIMP-low tumours had significantly more KRAS mutations as compared to other groups, CIMP-high (≥ 4/5 promoter regions methylated) or CIMP-negative (0/5 promoter regions methylated)." (PMID 23096130, 2013).
tumor (continued). "Mutations were detected in 72 (31.9%) tumours for KRAS, in 6 (2.65%) for BRAF, in 7 (3.1%) for NRAS and in 37 (16.4%) for PIK3CA." (PMID 23374602, 2013). "In these patients, codon 13 mutations were overrepresented when compared with the overall KRAS-mutated tumor population." (PMID 23437064, 2013). "Mutations in EGFR and KRAS detected in tumors embedded in paraffin blocks and fresh-frozen tumor specimens appear to be mutually exclusive." (PMID 23817662, 2013). "We also agreed with the findings of Yamauchi et al13, as all our cecal tumours possessed KRAS mutations, with variable levels of methylation." (PMID 23096130, 2013). "While KRAS mutations have been demonstrated to signify Type 1 tumours, and hence, generally associated with a more favourable clinical course, few studies have investigated the prognostic value of KRAS mutation status in EOC." (PMID 23800114, 2013). "The NCCN and ASCO guidelines are somewhat divergent on this point with the ASCO guidelines stating that “all patients with metastatic colorectal carcinoma who are candidates for anti-EGFR antibody therapy should have their tumor tested for KRAS mutations...”." (PMID 24403261, 2013). "In our model system, we have shown that the molecular nature of KRAS mutations clearly influences the vascular strategy devised by the tumour cell." (PMID 23506169, 2013). "The present study describes an optimized method for isolating peripheral blood circulating tumor cells (CTCs) and performing KRAS mutation analysis." (PMID 24179521, 2013). "In our analyses, we have compared the survival of BRAF/KRAS-mutated population with that of the double-wild type population, while controlling for several other parameters (tumor site, T and N stage, grade and MSI status)." (PMID 24073892, 2013). "In this study, we have examined the occurrence, clinicopathological correlates and prognostic significance of KRAS mutation status in invasive tumours from 153 incident EOC cases from two prospective, population-based Swedish cohorts." (PMID 23800114, 2013). "One tumor did have CSMD1 mutation allele concentrations that were less than the KRAS mutant allele concentration, perhaps indicating that the CSMD1 mutations in this tumor occurred after the KRAS mutations." (PMID 23505554, 2013). "In summary, there is a growing body of evidence to suggest that EGFR inhibitor-induced KRAS mutations that associates with tumor recurrence." (PMID 24304820, 2013). "Based on the generated phosphosubstrate profiles, a binary class partition model discriminated correctly between tumor KRAS/BRAF wild-type and mutation status in 67% of cases." (PMID 23226389, 2012). "The sensitivity, specificity and accuracy for detecting KRAS mutations in peripheral blood and tumour tissue samples were 61.5, 93.1 and 83.3%, respectively." (PMID 23226727, 2012). "The use of tumour KRAS mutation status as a biomarker for the efficacy of cetuximab-based regimens in this setting requires further investigation." (PMID 23077464, 2012). "We have previously excluded a discordance in KRAS mutation status between the primary tumour and corresponding metastases as an explanation for the heterogeneous response rate in patients with KRAS wild-type tumours." (PMID 22804917, 2012). "We correlated increased AURKA-CN in mCRC tumours with KRAS mutation status, overall and progression-free survival (OS, PFS)." (PMID 22240781, 2012). "KRAS point mutations were detected in primary tumour tissue samples of 13 patients (31.0%) and in peripheral blood samples of 10 patients (23.8%)." (PMID 23226727, 2012). "In total, 219 of the 394 patients (55.6%) had WT KRAS tumours, while 175 patients (44.4%) had some type of mutation." (PMID 23174912, 2012). "It has been shown that metastatic foci of tumor should have the same KRAS mutation as their original primary tumor." (PMID 23119210, 2012).